CD86 (CD86 molecule)
Diseases named in the same sentence as CD86 in open-access papers (continued):
Sharing a sentence is not in itself a finding about the gene and the disease.
cancer (continued). "We analyzed cancer tissue samples from 79 NSCLC patients using multiplex fluorescence (mIF) staining to visualize various SHP-2+ TAM subpopulations (CD68+SHP2+, CD68+CD86+, CD68 + 206+, CD68+ CD86+SHP2+, CD68+ CD206+SHP2+) and T cells (CD8+ Granzyme B +) of immune cells." (PMID 38799432, 2024). "The studies conducted by our research team on the interaction between CTLA-4 and CD86 in the course of CLL in the context of EBV reactivation, as well as the currently presented studies, show how important this pathway is in inhibiting the anti-cancer response." (PMID 37835480, 2023). "Interestingly, among pan-cancer, LGG showed the most significant correlation between GLA with CD86 (P=4.52e-27), CSF1R (P=8.17e-09),CCL2 (P=3.98e-14), CD68 (P=2.37e-34), IL10 (P=3.29e-21), IRF5 (P=8.5e-25), CD163 (P=3.8e-26), VSIG4 (P=9.17e-16) and MS4A4A (P=1.39e-21)." (PMID 37057282, 2023). "Based on our findings that AIF-1 expression is positively correlated with the expression of CD28, CD84, CD86, and LAIRI in several cancer types, we hypothesize that further investigation into the potential association between AIF-1 and these immune regulators would be promising." (PMID 37014322, 2023). "One important highlight is the observation that HDAC inhibition could improve cancer cells’ immune response via the regulation of the expressions of tumor antigens, including CD40, CD80, CD86, MHC, ICAM-1 and MICA/B, which drive the elimination of cancer cell proliferation through the immune system." (PMID 35158821, 2022). "Interestingly, the expression of CD206, CD86, CCR2 and C1QC expression in the Apoe-/- mice non-cancer model compared with Apoe+/+ mice was also decreased, indicating that changes in macrophages in the spleen and TAM might be consistent." (PMID 36147474, 2022). "It is known that HLA-ABC is crucial for proper presentation of specific antigens on the cancer cell surface for recognition by cytotoxic CD8 T cells, and that full activation of CD8 T cells requires both expression of HLA-ABC and expression of the T cell costimulatory molecule CD80 or CD86." (PMID 35954154, 2022). "This cytokine is frequently upregulated in cancers and has been shown to directly affect the function of APCs by inhibiting the expression of major histocompatibility complex (MHC) class II and costimulatory molecules CD80/B7-1 and CD86/B7.2, which in turn induces immune suppression or tolerance." (PMID 34079545, 2021). "Lack of CD86 could lead to T cell inactivation and nonresponse to tumor cells, and thereby allows malignant progression of cancer." (PMID 25369324, 2014). "In cancer patients, inflammatory changes indicate that IDO may be induced by soluble factors including IFNγ, TNF-α, IL-1β, soluble CD40 ligand (sCD40L) and CTLA-4 ligation to CD80/CD86 expressed by DC." (PMID 24147117, 2013). "Interestingly, we found that a significantly higher proportion of PRAME overexpressing cancer cells express immune checkpoint ligands such as PD‐L1, CD86, GAL‐9 and VISTA, which may in part explain the reduced T cell mediated activation and killing of PRAME overexpressing cancer cells." (PMID 34612587, 2021). "When we cocultured APG-2575-treated cancer cells with IL-4-activated macrophages, APG-2575-treated cancer cells did not alter the expression of CD86 and CD206." (PMID 38062129, 2024). "Cancer-free LNs harbour fewer CD4+ T cells, CD8+ T cells, CD80+, CD86+ and CD40+ immune cells and DCs which do not show characteristics associated with effective antigen presentation." (PMID 36139665, 2022). "The agonistic CD28 ligands B7.1 (CD80) and B7.2 (CD86), physiologically expressed on APCs, are missing on most cancer cells with the consequence that the CD3ζ CAR upon binding to cancer cells does not provide the costimulation required for full activation." (PMID 24273543, 2013).
cancer (continued). "T-DXd, but not trastuzumab, enhanced CD86 and HLA-DR expression in TDDCs in the coculture setting of NCI-N87 cells and TDDCs, indicating an indirect immunomodulatory effect of T-DXd on DC functionality through cancer cells." (PMID 39449023, 2024). "CD86, a ligand of T cell surface receptor CTLA4, was not expressed on cancer cells." (PMID 37762490, 2023). "Interestingly, CD86 was not decreased when DC was cultured in the presence of Epithelial Growth Factor (EGF), another growth factor involved in cancer development (data not shown)." (PMID 34771724, 2021). "Importantly, the ligands of CTLA-4 B7-1 (CD80) and B7-2 (CD86) are expressed on antigen presenting cells (APC) but not on cancer cells, whereas the ligands of PD-1, PD-L1 and PD-L2, are expressed on APC and on cancer cells." (PMID 27510264, 2016). "Similarly, ligands for CTLA4 (CD86 and CD80) were almost never expressed in cancer cells." (PMID 31427603, 2019).
bacterial infection (12 papers, 2016 to 2025). "Of note, the increased expression of CD86 in DCs resulted in improved phagocytic capacity during bacterial infections." (PMID 39794305, 2025). "Since lncRNAs could regulate the immune response against bacterial infection, we also validated the function of novel lncRNA TCONS_00007391, a regulator of CD86 identified in this study, by gene silencing and overexpression." (PMID 38326918, 2024). "M1-like macrophage surface marker CD86 and M2-like macrophage surface marker CD206 were observed to analyze the polarization typing of macrophages after bacterial infection." (PMID 34722780, 2021). "In the bacterial infection model, DC expression of CD83, CD40 and CD86 recovered by D5 to baseline levels." (PMID 32180339, 2020). "After examination of coactivators in monocytes after bacterial infection, we found reduced expression of coactivators (i.e., CD40, CD86, MHC-II, and CD14) from TSC1 KO mice and WT mice." (PMID 27746591, 2016). "Su3118 also did not significantly change the mRNA level of Cd206 or Cd86 in macrophages in response to bacterial infection or LPS/IL4 treatment." (PMID 41298379, 2025).
immune dysfunction (8 papers, 2016 to 2024). "Immune dysfunction is associated with defective CD86 expression in monocytes, leading to B7/28 pathway malfunction and impaired antigen-presenting function." (PMID 34979975, 2022). "Impaired recognition of pathogen-associated molecular patterns (PAMPs) to active innate immune responses, reduced expression of co-stimulatory molecules (CD80, CD86) and reduced antigen presenting capability, have also been reported to contribute to uremic immune dysfunction." (PMID 30619252, 2018). "Considering that T cell-stimulating factor such as CD80, CD86, and OX40L are positively regulated by PU.1 in DCs, PU.1 knockdown may be a favorable strategy in some immune disorders." (PMID 27708417, 2016).
infectious disease (6 papers, 2014 to 2024). A disorder directly resulting from the presence and activity of a microbial, viral, or parasitic agent in humans. "Further review of the ‘immune response’ GO cluster and genes within this category (CD1A, CD80, CD86, and HLA-DQB1) revealed related pathways which were in the same biological process associated with numerous autoimmune and infectious diseases." (PMID 38448477, 2024). "Our results confirm that, in response to cocktail cytokines, ILC2 upregulated CD86 and PD-L1, as observed in ILC2 from IL-33-treated mice and humans in infectious diseases, leading to an increase in the effector response." (PMID 38725998, 2024). "Taken together, in both autoimmune and infectious diseases a substantial amount of data is available on the differential regulation of CD80 vs. CD86, supporting our hypothesis of deleterious and protective roles for CD80+ and CD86+ B cells, respectively, in HAM/TSP pathogenesis." (PMID 24472094, 2014).
hematological malignancies (5 papers, 2019 to 2025). "Later, a soluble isoform of CD86 (sCD86) that lacks the exon 6 encoding the transmembrane region was found in the peripheral blood in healthy people and patients with hematological diseases." (PMID 40635602, 2025). "Usually, flow cytometry is used to identify CD86 expression on B or plasma cells in hematologic malignancies, with a detection rate of 58.0% or 47.5%." (PMID 36428666, 2022). "This study discusses the importance of CD86 expression in hematological malignancies." (PMID 40635602, 2025). "The ligands for PD-1, programmed cell death ligand 1 (PD-L1) and programmed cell death ligand 2‚ as well as the ligands for CTLA-4, B7-1 (CD80), and B7-2 (CD86), are upregulated in both solid tumors and hematological malignancies." (PMID 33931473, 2021).
cardiovascular disease (3 papers, 2016 to 2024). "CD86, driving the atherogenic process in the adaptive immune system, and BATF relate MS disease with cardiovascular disease risk factors, high-density lipoprotein cholesterol (CD86), and systolic blood pressure (BATF)." (PMID 35008743, 2021).
hematologic cancers (3 papers, 2021 to 2024). "Whereas RAJI-CD80/CD86-negative and NCI-H929 cells were utilized with bsAbs targeting hematologic cancers, such as CD20xCD3 and BCMAxCD3, respectively." (PMID 34257348, 2021).
neurological disorders (2 papers, 2014 to 2021). "We have previously reported that transgene-derived constitutive expression of the co-stimulator B7.2 (CD86) on antigen-presenting cells of the nervous tissues can cause spontaneous neurological disorders in mice." (PMID 33752705, 2021).
adenocarcinoma (1 paper, 2025). A common cancer characterized by the presence of malignant glandular cells. "Subgroup analysis restricted to patients with adenocarcinoma or those that did not have a complete response to CRT yielded similar results with the notable exception being enrichment of HLA-DR/CD80+/CD86+ expression in patients without a history of relapse." (PMID 39751903, 2025).
heart (1 paper, 2017). "Of note, the ratio of M2-like CXCR4-EGFP+CD11b+/CD206+ cells to inflammatory M1-like CD11b+/CD86+ cells increased by 2.6-fold after DMOG-induced PH inhibition compared to infarcted control mice, suggesting an improved fine-tuning of reparative M2-like cells in the ischemic heart after 7 days." (PMID 28550361, 2017).
kidney disease (1 paper, 2020). "On the other hand, as the kidney disease progresses, these macrophages polarize to M2 (CD86-/CD163+/CD206+) which have an anti-inflammatory role promoting the healing of damaged tissue and are therefore considered pro-fibrotic." (PMID 32340145, 2020).
CD86 also shares sentences with these, for which no sentence is quoted: multiple myeloma (13 papers); kidney (4); inflammation (3); Atherosclerotic lesion (2); autoimmune peripheral neuropathy (2); bladder urothelial carcinoma (2); bronchiolitis obliterans (2); cardiac hypertrophy (2); E. coli infection (2); endocervical adenocarcinoma (2); fungal infection (2); graft versus host disease (2); hepatitis C (2); hypertrophy (2); lung squamous cell carcinoma (2); lymphedema (2); lymphopenia (2); malignant glioma (2); morbid obesity (2); myelodysplastic syndrome (2); neuropathy (2); Pancytopenia (2); primary biliary cholangitis (2); psoriatic arthritis (2); pulmonary arterial hypertension (2); retinal degeneration (2); uveal melanoma (2); vascular disorder (2); abscesses (1); acquired immunodeficiency (1).
A further 102 diseases each share a sentence with CD86 in 1 paper.